MAN2A1 (mannosidase alpha class 2A member 1)
Description:
Catalyzes the first committed step in the biosynthesis of complex N-glycans. It controls conversion of high mannose to complex N-glycans; the final hydrolytic step in the N-glycan maturation pathway.
Synonyms: AMan II; MANA2; GOLIM7; MANII
Tractability: Antibody: UniProt predicts a signal peptide or a membrane-spanning region. PROTAC: ubiquitination databases record sites on it; its protein half-life has been measured; a small molecule that binds it is known.
Target class: Enzyme; Hydrolase
Gene: Protein-coding gene on chromosome 5 (109,689,375 to 109,869,625, forward strand). Ensembl gene ENSG00000112893.
Subcellular location: Golgi apparatus membrane
Subcellular location (Human Protein Atlas): Golgi apparatus
Pathways (Reactome):
Disease: Maturation of spike protein
Metabolism of proteins: Reactions specific to the complex N-glycan synthesis pathway
Vesicle-mediated transport: Intra-Golgi traffic
Gene Ontology:
Molecular function: mannosyl-oligosaccharide 1,3-1,6-alpha-mannosidase activity; alpha-mannosidase activity; carbohydrate binding; hydrolase activity; hydrolase activity, hydrolyzing N-glycosyl compounds; mannosidase activity
Biological process: N-glycan processing; viral protein processing; carbohydrate metabolic process; mannose metabolic process
Cellular component: extracellular exosome; Golgi apparatus; Golgi medial cisterna; membrane; Golgi membrane; cis-Golgi network; extracellular region
Genetic constraint (gnomAD): Loss-of-function variants: 42 observed, 72.29 expected, observed/expected ratio (o/e) 0.58, 90% interval 0.45 to 0.75. The upper end of that interval is the gene's LOEUF score, 0.75, which puts it in group 3 of 6, group 1 being the genes least tolerant of losing a copy. Missense variants: 777 observed, 850.05 expected, observed/expected ratio (o/e) 0.91, 90% interval 0.86 to 0.97. Synonymous variants: 352 observed, 308.95 expected, observed/expected ratio (o/e) 1.14, 90% interval 1.04 to 1.24.
Homologues: Orthologues: chimpanzee MAN2A1 (99% identical), macaque MAN2A1 (98% identical), dog MAN2A1 (85% identical), guinea pig MAN2A1 (81% identical), pig MAN2A1 (81% identical), mouse Man2a1 (81% identical), rat Man2a1 (78% identical), rabbit MAN2A1 (78% identical), tropical clawed frog man2a1 (69% identical), zebrafish man2a1 (62% identical), Drosophila melanogaster alpha-Man-IIa (38% identical), Caenorhabditis elegans aman-2 (38% identical), and 1 more. Paralogues in human: MAN2A2 (54% identical), MAN2B1 (24% identical), MAN2B2 (23% identical), MAN2C1 (15% identical).
Diseases named in the same sentence as MAN2A1 in open-access papers:
MAN2A1 is named in the same sentence as 44 diseases in open-access papers, as found by Europe PMC text mining. Sharing a sentence is not in itself a finding about the gene and the disease. The quoted sentences say what the papers report.
liver cancer (8 papers, 2019 to 2025). An epithelial or non-epithelial malignant neoplasm that arises from the liver. "When coupled with somatic deletion of Pten, MAN2A1-FER expression induced spontaneous liver cancer in mice." (PMID 39082961, 2024). "MAN2A1-FER is a common recurrent fusion in liver cancer, esophageal adenocarcinoma, and non-small cell lung cancer, and has carcinogenic effects." (PMID 34381020, 2021). "This approach led to the partial remission of xenografted human liver cancers when the animals were treated with reagents targeting the breakpoint of the MAN2A1-FER fusion gene." (PMID 31164957, 2019). "The expression of MAN2A1-FER was frequently detected in primary liver cancer and serum samples." (PMID 39082961, 2024). "Targeting the cancer-specific ectopic phosphorylation sites of PDGFRA induced by MAN2A1-FER may hold promise as an effective treatment for liver cancer." (PMID 39082961, 2024). "Among the eight fusion genes, MAN2A1-FER, TRMT11-GRIK2, and CCNH-C5orf30 were shown as the most frequent in HCC samples, and the relative fusion transcripts in the serum samples of liver cancer patients were identified as circulating, cell-free RNA." (PMID 39941182, 2025). "MAN2A1-FER fusions have been identified in prostate cancer, liver cancer, esophageal cancer, and other types of malignant tumors." (PMID 39963268, 2025). "Fusion genes such as MAN2A1–FER, PTEN–NOLC1, and SLC45A2–AMACR are the oncogenic drivers of liver cancer development." (PMID 38537933, 2024). "The introduction of MAN2A1-FER increased cancer cell proliferation in vitro and promoted cancer growth, invasion, and metastasis in xenografted liver cancer animal models." (PMID 39082961, 2024). "The frequency of MAN2A1-FER is higher in esophageal adenocarcinoma (25.9%), liver cancer (15.7%), and non-small cell lung cancer (16.8%)." (PMID 34381020, 2021). "In this study, we showed that the fusion transcripts of MAN2A1-FER, CCNH-C5orf30 and SLC45A2-AMACR were detected in the serum samples of liver cancer patients as circulating cell-free RNA." (PMID 31164957, 2019). "MAN2A1-FER was detected in 15% of human HCC samples, and this fusion protein was shown to be a driver of mouse liver cancer." (PMID 31164957, 2019). "Using CRISPR/Cas9 technology to target MAN2A1-FER fusion gene inhibits tumor proliferation and metastasis in the mouse models of prostate and liver cancer." (PMID 30873379, 2019).
prostate carcinoma (8 papers, 2015 to 2025). A carcinoma that arises from epithelial cells of the prostate gland. "Future clinical outcome analysis may reveal whether blood MAN2A1-FER is associated with poor clinical outcomes of the prostate cancer." (PMID 34417538, 2021). "When fused with FER, MAN2A1 transforms into an oncogene; around 80% of prostate cancer patients with MAN2A1-FER have exhibited a dismal clinical prognosis according to earlier studies." (PMID 38627854, 2024). "They used Cas9D10A-based genome editing to introduce the suicide gene HSV1-tk, encoding the prodrug-converting enzyme herpes simplex virus type 1 thymidine kinase into the breakpoints of TMEM135-CCDC67 and MAN2A1-FER fusions in human prostate cancer and hepatocellular carcinoma cells, respectively." (PMID 35267426, 2022). "MAN2A1-FER, a fusion gene encoding for a tyrosine protein kinase, was present in 82.3% (121/147) blood samples from the prostate cancer patients, representing the most frequent fusion transcript detected in the blood of prostate cancer patients." (PMID 34417538, 2021). "Eighty-two percent blood samples from the prostate cancer patients were positive for MAN2A1-FER transcript, while 41.5% and 38.8% blood samples from the prostate cancer patients were positive for SLC45A2-AMACR and Pten-NOLC1, respectively." (PMID 34417538, 2021). "For MAN2A1-FER, 88% (22/25) prostate cancer samples were positive, while only 68% (17/25) matched blood samples were detected to contain the same transcript." (PMID 34417538, 2021). "The high positive prediction rates for MAN2A1-FER (88.2%), SLC45A2-AMACR (75%) and Pten-NOLC1 (90.9%) between blood samples and the primary prostate cancer samples suggests that the source of the fusion transcripts in the blood samples is likely prostate cancer." (PMID 34417538, 2021). "The most sensitive fusion transcript is MAN2A1-FER, reaching 82.3%, while several fusion transcripts such as TRMT11-GRIK2 were mostly not detectable in the blood even they were present in the prostate cancer samples." (PMID 34417538, 2021).
hepatocellular carcinoma (5 papers, 2019 to 2023). A malignant tumor that arises from hepatocytes. "Among 8 fusion genes, MAN2A1-FER, TRMT11-GRIK2 and CCNH-C5orf30 appear most frequently in hepatocellular carcinoma samples." (PMID 31164957, 2019). "In addition, the SSBP2 (single-stranded DNA binding protein 2)–FER fusion and the MAN2A1 (mannosidase alpha class 2A member 1)–FER fusion have also been identified in leukemia and hepatocellular carcinoma patients, respectively." (PMID 37196766, 2023).
breast carcinoma (3 papers, 2018 to 2024). "This possibility was supported by the TCGA patient dataset findings, demonstrating the associations between high α-mannosidase II (MAN2A1) expression levels and reduced survival in breast cancer patients." (PMID 37830552, 2023). "In this manner, MAN2A1 has been reported to be altered in glioblastoma, GALNT1 is altered in bladder cancer, C1GALT1C1 is altered in colorectal cancer, and UGT8 is altered in breast cancer." (PMID 30038662, 2018).
autoimmune disease (2 papers, 2022 to 2025). A disorder resulting from loss of function or tissue destruction of an organ or multiple organs, arising from humoral or cellular immune responses of the individual to their own tissue constituents. "In contrast, Man2a1 deficiency in mice is well-tolerated at early ages, however, these animals develop dyserythropoiesis and in later adult life autoimmune disease." (PMID 35967980, 2022). "MAN2A1 has been previously identified as a regulator of the inflammatory response and autoimmune diseases." (PMID 39963268, 2025). "Mice lacking MAN2A1 exhibit a deficiency in N-glycans on red blood cells, resulting in anemia and the development of a late-onset autoimmune disease that closely resembles systemic lupus erythematosus (SLE)." (PMID 39963268, 2025).
cervical cancer (2 papers, 2018 to 2025). A primary or metastatic malignant neoplasm involving the cervix. "Interestingly, two core genes, RIBC2 and MAN2A1, were further identified as key players in the onset and progression of cervical cancer." (PMID 39963268, 2025).
endometrial cancer (2 papers, 2018 to 2025). Primary or metastatic malignant neoplasm involving the endometrium (mucous membrane that lines the endometrial cavity). "The result suggested that MAN2A1 and RIBC2 may act as a risk or protective factor in the occurrence, development, and prognosis of endometrial cancer." (PMID 39963268, 2025). "FUT4 is increased in leukaemia, gastric, breast and colorectal cancer; UGT2B17 is increased in endometrial cancer; POFUT1 is increased in glioblastomas and oral squamous cell carcinoma, and MAN2A1 is decreased in glioblastoma." (PMID 30038662, 2018).
glomerulonephritis (2 papers, 2022 to 2025). A renal disorder characterized by damage in the glomeruli. "For instance, MAN2A1 is involved in the development and progression of glomerulonephritis." (PMID 39963268, 2025).
ovarian carcinoma (2 papers, 2021 to 2022). A malignant neoplasm originating from the surface ovarian epithelium. "Although the frequency of MAN2A1-FER fusion in ovarian cancer is only 1.7% (1/60), it appears in a variety of tumors." (PMID 34381020, 2021). "The MAN2A1-FER fusion in ovarian cancer can significantly enhance tyrosine kinase activity." (PMID 34381020, 2021). "The fusion genes that have been identified in ovarian cancer are PCMTD1-CCNL2, ANXA5-CCNA2, CCN4-NRG4, SLC25A40-ABCB1, DPP9-PPP6R3, MAN2A1-FER, CDKN2D-WDFY2, BCAM-AKT2, and FHL2-GLI2." (PMID 34381020, 2021).
dementia (1 paper, 2023). Loss of intellectual abilities interfering with an individual's social and occupational functions. "Importantly, five of these pre-mRNAs (DOCK1, HOMER1, MAN2A1, RTN4, and ST18) were also found to correlate with dementia severity in the parietal cortex, suggesting that these circRNAs in general correlate with AD progression." (PMID 37266374, 2023).
gastritis (1 paper, 2025). Inflammation of the stomach. "A different model, designed to predict cancer or preneoplasia vs. healthy or gastritis, yielded an even higher mAUROC of 83.9% (73.9–93.9% (95% CI)) and was based on the plasma concentrations of ARG1, HPT, CA2, MAN2A1, and LBP." (PMID 41155404, 2025).
lymph node metastases (1 paper, 2024). "The high-confidence driver genes RHPN2, MUC16, and MUC4 were significantly mutated in both small- and large-sized rNEN specimens, whereas mutations in MAN2A1, and BAG2 were only identified in large-sized specimens diagnosed with lymph node metastases." (PMID 39548061, 2024). "Moreover, HC-SMGs such as MUC19, MAN2A1 and HNRNPCL1 were exclusively mutated in rNEN-L patients with lymph node metastases, suggesting their involvement in the increasingly aggressive behavior of this disease." (PMID 39548061, 2024).
metastatic colorectal cancer (1 paper, 2025). "Furthermore, it has been observed that MAN2A1 is downregulated in metastatic colorectal cancer in contrast to non-metastatic colorectal cancer (CRC)." (PMID 39963268, 2025).
Obesity (1 paper, 2023). Accumulation of substantial excess body fat. "We also highlight context-specific regulatory effects for genes involved in metabolic (e.g. obesity, NTRK2,) and neurological (e.g. schizophrenia, MAN2A1,) diseases, and for genes with a role in biological processes such as adipogenesis (e.g. DEPTOR,)." (PMID 37543566, 2023).
prediabetes (1 paper, 2025). "However, within the progression analysis involving individuals transitioning from NGT to prediabetes or T2D, we observed that 2 out of 7 CpG sites—MAN2A1 and ABCG1—exhibited suggestive significance or nominal significance to prediabetes." (PMID 39827095, 2025).
type 2 diabetes (1 paper, 2005). "In the BSA treated NON mice, Man2a1 is up-regulated 1.4 fold, in a very similar manner to the up-regulation observed in kidneys of db/db mice with type 2 diabetes and albuminuria (1.4–1.7 or 1.8 reported in the literature)." (PMID 16371158, 2005).
virus infection (1 paper, 2022). "In addition, ELISA results showed that the interference of MAN2A1 down-regulated the secretion level of IFN-α in cells after virus infection significantly, suggesting that the expression of MAN2A1 affected the cellular immune response to a certain extent." (PMID 35163797, 2022).
cancer (15 papers, 2019 to 2025). A tumor composed of atypical neoplastic, often pleomorphic cells that invade other tissues. "MAN2A1, involved in N-linked oligosaccharide processing in the Golgi apparatus, may contribute to the metabolic reprogramming and altered glycosylation characteristic of cancer cells." (PMID 41155404, 2025). "The treatment of MAN2A1-FER–positive cancer HUH7 with one of the antibodies called 2-3B-G8 led to the deactivation of cell growth signaling pathways and cell growth arrest while having minimal impact on HUH7ko cells where MAN2A1-FER expression was disrupted." (PMID 39082961, 2024). "A computer analysed the data and classified them using ML, generating the hypothesis that four of the fusion transcripts (MAN2A1-FER ≤ 40, CCNH-C5orf30 ≤ 38, SLC45A2-AMACR ≤ 41, and PTEN-NOLC1 ≤ 40) were associated with a high probability of cancer." (PMID 39941182, 2025). "MAN2A1 has emerged as a therapeutic target for cancer treatment." (PMID 39628046, 2024). "MAN2A1 was reported to involve in glycosylation pattern in cancer cells, and its knockout strengthened the PD-L1 blockade therapy and immune response against cancer cells." (PMID 34539936, 2021). "A recent study found Man2a1-null cancer cells are more sensitive to T cell-mediated tumor killing." (PMID 33777952, 2021). "The MAN2A1-FER fusion facilitates the transport of the FER kinase to the Golgi apparatus, where it activates and promotes cancer through the epidermal growth factor receptor (EGFR) signaling pathway." (PMID 39963268, 2025). "Previous studies showed that gene fusion MAN2A1-FER, Pten-NOLC1 and SLC45A2-AMACR are the cancer drivers." (PMID 34417538, 2021). "As a key immunomodulatory gene, the absence of MAN2A1 in cancer cells increases their sensitivity to T cell-mediated killing." (PMID 35163797, 2022). "Second, single pathway blockade through small molecules may not be sufficient to kill off HCC cancer cells that are positive for MAN2A1-FER because of multiple bypasses of the growth signaling." (PMID 39082961, 2024). "In this way, CRISPR-Cas9 only induces DSBs in cancer cells (not normal cells) that contain the TMEM135-CCDC67 and MAN2A1-FER fusion genes, which greatly reduced the off-target effects." (PMID 30911676, 2019). "Moreover, HEXA, HEXB, MAN2A1, and MAN2B1 were overexpressed in cancer relative to healthy stomachs from individuals without gastric pathologies." (PMID 41041068, 2025).
tumor (10 papers, 2017 to 2025). "MAN2A1 has been shown to be involved in the immune regulation of tumors, and inhibition of MAN2A1 can enhance the tumor’s immune response to anti-PD-L1 drugs." (PMID 34381020, 2021). "However, the inhibition effect of tumor growth by 2-3B-G8-MMAE was largely eliminated after MAN2A1-FER was disrupted." (PMID 39082961, 2024). "Among them, MAN2A1 (mannosidase alpha class 2A member 1) is a Golgi enzyme that converts high mannose into a complex structure of N-glycans to mature and glycosylate membrane proteins, which plays an important biological function in tumor and other immune processes." (PMID 35163797, 2022). "Notably, neoplasia patients exhibited a tendency to upregulate several glycogenes, including MGAT1, MAN2A1, MAN2B1, and MGAT2 (which contributed to the clustering), associated with the initial steps of the biosynthesis of more complex N-glycan structures." (PMID 40087977, 2025). "Despite the apparent oncogenic activity of MAN2A1-FER, the mechanism of its tumor-promoting activity remains unclear." (PMID 39082961, 2024). "Further evaluating the microarray data of the scid and the select group, we observed that many genes which are crucial for glycosylation show an altered expression: for example, MAN1A1, MAN2A1, and GALNT 5 and 7 were downregulated in Fra-2 cl 1 scid primary tumours, whereas MGAT4A was upregulated." (PMID 34693476, 2022).
infection (1 paper, 2022). The state of being infected such as from the introduction of a foreign agent such as serum, vaccine, antigenic substance or organism. "The results suggested that the expression of MAN2A1 may mainly regulate the infection of SIV by regulating the replication and proliferation of SIV instead of innate immune response." (PMID 35163797, 2022).
MAN2A1 also shares sentences with these, for which no sentence is quoted: Alzheimer disease (2 papers); glioblastoma (2); leukaemia (2); anemia (1); atrophic gastritis (1); bladder cancer (1); colon cancer (1); colorectal cancer (1); cystic fibrosis (1); esophageal adenocarcinoma (1); esophageal cancer (1); fibroblastic disorder (1); lung carcinoma (1); lupus nephritis (1); melanoma (1); non-small cell lung carcinoma (1); oral squamous cell carcinoma (1); renal cell carcinoma (1); renal fibrosis (1); respiratory failure (1); SARS-CoV Infections (1); schizophrenia (1); systemic lupus erythematosus (1); type 1 diabetes (1).